IL20 (interleukin 20)
Diseases named in the same sentence as IL20 in open-access papers (continued):
Sharing a sentence is not in itself a finding about the gene and the disease.
breast tumor (2 papers, 2019 to 2025). "Expression of IL-20 and all its receptor chains is increased in breast tumor tissue and correlates with a poorer prognosis." (PMID 40806452, 2025). "One paper evaluated the function of IL-20, a cytokine with a pro-inflammatory effect structurally related to the IL-10 family, and high expression levels of IL-20 were found in primary breast tumor tissue and bone-metastatic tissue." (PMID 31847214, 2019). "As previously reported, IL-20 was highly expressed in BC tissue and enhanced breast tumor growth in in vitro and in vivo models, triggering the activation of both signaling pathways involved in cellular proliferation (see Section 4.1.2) and antiapoptotic-associated signals such as Bcl-XL and Bad." (PMID 40806452, 2025).
chronic kidney disease (2 papers, 2020 to 2025). Impairment of the renal function secondary to chronic kidney damage persisting for three or more months. ".A new study shows that IL-20, another interleukin, can affect the development of chronic kidney disease." (PMID 40027896, 2025). "We also demonstrated the increased production of Il19, Il20, and Il24 in the kidney samples from the different animal models of acute and chronic kidney disease." (PMID 32306980, 2020). "Serum IL-20 levels were much higher in people with advanced-stage chronic kidney disease." (PMID 40027896, 2025).
degenerative disc disease (2 papers, 2015 to 2018). "At the same time, we found with the advance of disc degeneration, the content of IL-20 increase, but proteoglycan decrease gradually, indicating IL-20 was significantly correlated with the degeneration grade of intervertebral discs." (PMID 25878634, 2015). "In addition, with the advance of disc degeneration, the content of IL-20 increase, but proteoglycan decrease gradually (Table-III)." (PMID 25878634, 2015). "In patients with degenerative disc disease, the content of IL-20 and proteoglycan has significant correlation with degeneration grade of lumbar disc, and IL-20 may promote the degeneration of lumbar disc by affecting the synthesis of proteoglycan." (PMID 25878634, 2015). "In addition, the process of IL-20 affecting the disc degeneration may be correlated closely with proteoglycan." (PMID 25878634, 2015). "However, it is not clear whether IL-19 is also more potent than IL-20 in vivo for disc degeneration." (PMID 30250404, 2018).
diabetic nephropathy (2 papers, 2020 to 2024). "Nonetheless, IL-20 has been identified as a driver of podocyte injury in diabetic nephropathy." (PMID 38672094, 2024).
dry eye (2 papers, 2022 to 2024). "Since inflammation and apoptosis are considered to be important mechanisms involved in dry eye, we aimed to explore the role of IL-20 in the pathogenesis of DED and evaluate the therapeutic potential of the anti-IL-20 monoclonal antibody (mAb) 7E for DED treatment." (PMID 35681232, 2022). "Additionally, whether the levels of IL-20 in tears can be used as a biomarker for the diagnosis or prognosis of the dry eye still needs the support of more clinical samples in further study." (PMID 35681232, 2022). "In addition, IL-20 was significantly increased in the tears of animal models with BAC-induced dry eye; as IL-20 can induce an inflammatory response, including infiltration and activation of macrophages, it has been suggested that it is a potential treatment target in patients with dry eyes." (PMID 39596346, 2024). "Based on our observation that IL-20 was upregulated in DED mice, we investigated the involvement of IL-20 in DED progression and examined the therapeutic effects of 7E on the BAC-induced evaporative dry eye mouse model." (PMID 35681232, 2022). "To test whether IL-20 is altered by hyperosmolarity, we incubated HCE-2 cells, a human corneal epithelial cell line, with sodium chloride to induce hyperosmotic stress and mimic dry eye conditions in vitro." (PMID 35681232, 2022).
fibrosis (2 papers, 2020). the formation of excess fibrous connective tissue in an organ or tissue in a reparative or reactive process. "To investigate the effect of IL-20 on the pancreatic fibrosis occurring during PDAC, we evaluated the distribution of alpha-smooth muscle actin (αSMA), a hallmark of fibrosis." (PMID 32929072, 2020). "To understand the mechanisms leading to increased production of IL19, IL20 and IL24 in the injured kidney we investigated the effect of several fibrosis related factors on their expression in healthy and CKD-derived PBMCs, as well." (PMID 32306980, 2020).
Hyperkeratosis (2 papers, 2013 to 2022). Hyperkeratosis is a histopathological term defining a thickened stratum corneum and may be present in many different skin conditions, with many possible overlaps. "Thus, up-regulation of IL-20 may contribute to the proliferation of keratinocytes and development of a thickened epidermis (hyperkeratosis) and the scaly and crusted skin associated with advanced scabies." (PMID 23940705, 2013).
inflammatory skin disease (2 papers, 2007 to 2013). Inflammatory skin disorders covers a broad category that includes many conditions ranging in severity, from mild itching to grave medical health complications These disorders are common in people of all ages and races. "In contrast, IL-19 and IL-20 were strongly induced in samples from patients with inflammatory skin disease while freshly isolated keratinocytes expressed robust levels of IL-24 and IL-20." (PMID 18074024, 2007).
liver cirrhosis (2 papers, 2017 to 2020). "IL-20 acts as a pivotal factor in fibrogenesis and is involved in renal fibrosis and liver cirrhosis through upregulating TGF-β production." (PMID 32408881, 2020). "IL-20 is a proinflammatory cytokine involved in renal fibrosis and liver cirrhosis through its role in upregulating TGF-β1 production." (PMID 32408881, 2020). "IL-20 expression in HCC patients was correlated with liver cirrhosis, tumor multiplicity and differentiation, and tumor stages." (PMID 29242565, 2017).
lupus (2 papers, 2013 to 2022). "Renal IL-20 overexpression was also observed in lupus patients." (PMID 36015084, 2022). "The gene cluster that includes interleukin 10 (IL10), IL19, IL20 and IL24 is located on chromosome 1q31-32, a genomic region that is linked with susceptibility to systemic lupus erythematosus (SLE, OMIM 152700)." (PMID 24130510, 2013).
lupus nephritis (2 papers, 2020 to 2022). Glomerulonephritis in the context of systemic lupus erythematosus. "The IL-20 signaling axis influences the crosstalk between lymphocytes and epithelial cells, including facilitating the infiltration of immune cells to the kidneys in murine lupus nephritis models." (PMID 36199584, 2022). "IL-20 expression is positively correlated with the severity of lupus nephritis, which suggests that IL-20 may participate in the development of lupus nephritis." (PMID 32028746, 2020). "Additionally, the cellular sources of IL-20 are mesangial cells and macrophages in the kidney of patients with lupus nephritis." (PMID 32028746, 2020).
melanoma (2 papers, 2007 to 2021). A malignant, usually aggressive tumor composed of atypical, neoplastic melanocytes. "Since no Jak/STAT signalling was detected in any of the melanoma cell lines following IL-24 (or IL-19 and IL-20) treatment, the expression of the 3 possible receptor chains was analysed by standard RT-PCR, quantitative PCR (qPCR), Western Blot and FACS analyses." (PMID 18074024, 2007). "Using crude or affinity purified Hek-IL-24, again no increase in apoptosis or reduced proliferation was observed relative to untreated cells or cells treated with accordingly produced IL-20 and this was not surprising as the tested melanoma cell lines did not express functional IL-24 receptors." (PMID 18074024, 2007).
Obesity (2 papers, 2024 to 2025). Accumulation of substantial excess body fat. "Additionally, obesity was associated with reduced IL-20 methylation, highlighting the need for further investigation into how these demographic factors interact with the epigenetic effects of Tai Chi practice." (PMID 41551693, 2025). "In a mouse model of high obesity, anti-IL-20 mAb therapy improved glucose tolerance and reduced the number of local inflammatory cells and macrophages in adipose tissue." (PMID 38699038, 2024). "Thus, we investigate the effects of Tai Chi exercise on the methylation levels of the IL-20 promoter, while factoring in the influences of gender, age, and obesity." (PMID 41551693, 2025). "Our study acknowledges that while the primary focus was on Tai Chi exercise and IL-20 promoter methylation, factors such as age, gender, and obesity may influence methylation patterns and health outcomes." (PMID 41551693, 2025). "Men exhibited lower IL-20 methylation levels, while older age and obesity showed similar trends." (PMID 41551693, 2025). "This indicates a significant role of IL-20 in obesity-induced inflammation, which may be a useful treatment option for obese patients with metabolic disorders." (PMID 38699038, 2024).
oral cancer (2 papers, 2020 to 2024). "In their previous studies, they similarly found that IL-20 promoted tumor growth in HCC, breast and oral cancer, and anti-IL-20 mAb treatment in a mouse model of cancer effectively mitigated the release of inflammatory mediators, inhibited tumor growth, and improved survival rates." (PMID 38699038, 2024).
ovarian carcinoma (2 papers, 2021 to 2023). A malignant neoplasm originating from the surface ovarian epithelium. "IL-18 is the essential factor downstream IL-20/IL20RA signaling to prevent the ovarian cancer dissemination." (PMID 34114949, 2021).
pancreatic ductal adenocarcinoma (2 papers, 2020 to 2024). An infiltrating adenocarcinoma that arises from the epithelial cells of the pancreas. "In mouse models of pancreatic ductal adenocarcinoma, there was concordance between IL-20 and HCC pathology status, associated with increased tumor fibrosis, programmed cell death 1 ligand 1 expression, and decreased overall survival." (PMID 38699038, 2024). "Here, the authors show that high levels of IL-20 are associated with poor survival in patients with pancreatic ductal adenocarcinoma (PDAC) and that IL-20 blockade reduces tumor growth and alleviates cachexia symptoms in mouse models of PDAC." (PMID 32929072, 2020).
prostate adenocarcinoma (2 papers, 2015 to 2018). "Forty prostate adenocarcinoma tissue samples (stage II, n = 8; stage III, n = 32) were IHC stained with anti-IL–20 mAbs." (PMID 26440411, 2015).
Pruritus (2 papers, 2023). Pruritus is an itch or a sensation that makes a person want to scratch. "Among the up-regulated genes in this group, IL-20 is associated with IL-31-induced barrier disruption, and has also been related with pruritus in murine AD models." (PMID 36993985, 2023). "It was shown that the expression of genes encoding inflammatory mediators such as CCL4, CCL7, CCL8, CCL20, interleukin-19 (IL-19), IL-20, IL-26, IL-36A, IL-36G, and TNF-α) was unique to psoriatic skin with pruritus." (PMID 37834183, 2023).
renal fibrosis (2 papers, 2020). A final common manifestation of a wide variety of chronic kidney diseases characterized by glomerulosclerosis and tubulointerstitial fibrosis. "However, since IL-19 and IL-20 signal through the same receptor complexes it is also possible that they exert similar effects on the scar tissue formation, therefore further experiments are needed to clarify their role in the process of renal fibrosis." (PMID 32306980, 2020).
ulcerative colitis (2 papers, 2019 to 2022). An inflammatory bowel disease involving the mucosal surface of the large intestine and rectum. "The interleukin (IL)-20 subfamily of cytokines consists of IL-19, IL-20, IL-22, IL-24, and IL-26, and the expression of IL-20, IL-22, and IL-24 is reported to be higher in the colon of patients with ulcerative colitis." (PMID 31311100, 2019). "It has been found that the expression levels of IL-20, IL-22, and IL-24 are higher in the colon of patients with ulcerative colitis but that their roles in colonic epithelial renewal are not clearly understood." (PMID 31311100, 2019). "IL-20, IL-22, and IL-24 have been found to be higher in the colons of patients with ulcerative colitis, where mucosal epithelial damage is very common." (PMID 31311100, 2019). "We next evaluated whether IL-20 treatment impacts acute and spontaneous intestinal inflammation using different pre-clinical models of ulcerative colitis." (PMID 36613621, 2022). "IL-20 levels are reported to increase in the intestines of Ulcerative Colitis (UC) patients, however not much is known about its effects on intestinal epithelial cells." (PMID 36613621, 2022).
viral infection (2 papers, 2021). "Because IL-20 cytokines are associated with an increased clinical outcome of COPD and viral infection, we want to assess their physiopathologic role during viral exacerbation of COPD using WT and IL-20Rb KO mice." (PMID 34944654, 2021). "Additional experiments are required in order to analyze the epithelial permeability in a model of air–liquid interface after viral infection and the role of IL-20 cytokines." (PMID 34944654, 2021). "Since IL-20 cytokines are known to be involved in bacterial clearance, we checked on their involvement in the context of a viral infection." (PMID 34944654, 2021). "Previous reports showed that IL-20 cytokines facilitate bacterial lung infection, but their production and their role in COPD and viral infection has not yet been investigated." (PMID 34944654, 2021).
acne (1 paper, 2014). An inflammatory process of the sebaceous glands which is characterized by comedones, nodules, papules and/or pustules on the skin. "In our study elevated levels of IL-22 and IL-20 were found in acne lesions by RT-PCR." (PMID 25153527, 2014).
adrenal pheochromocytoma (1 paper, 2020). "To explore the role of IL-20 in axonal regeneration, we analyzed the expression of IL-20 and its receptors in PC-12 cells, a rat adrenal pheochromocytoma cell line that responds reversibly to nerve growth factor (NGF) by induction of the neuronal phenotype." (PMID 32408881, 2020).
alcoholic liver diseases (1 paper, 2020). A disorder caused by damage to the liver parenchyma due to alcohol consumption. "In both nonalcoholic and alcoholic liver disease models, interleukin-20 (IL-20) family cytokines reduce liver injury and inflammation." (PMID 32581074, 2020).
all (1 paper, 2022). "Exceptions were the association for Beta-NGF and all-cause dementia as well as the associations of CCL3, CCL20, and IL20-RA with vascular dementia, which became statistically significant with the best fitting function." (PMID 36085081, 2022).
Allergy (1 paper, 2019). An allergy is an immune response or reaction to substances that are usually not harmful. "Our results indicate that the IL-20-related cytokines are markers of PPD allergy because we found a correlation between IL-20-related cytokine expression and the severity of reactions in patients." (PMID 30755657, 2019).
autoimmune gastritis (1 paper, 2022). Inflammation of the body fundic mucosa of the stomach. "We compared serum levels of IL-19, IL-20, IL-26, IL-28A and IL-29 in 43 patients with PA and autoimmune gastritis, in 20 patients with IDA and no autoimmune gastritis, and in 47 HC." (PMID 35479078, 2022).
brain infarction (1 paper, 2021). Tissue necrosis in any area of the brain, including the cerebral hemispheres, the cerebellum, and the brain stem. "However, IL-20 expression was upregulated in the serum and brain tissue of rats after cerebral I/R, and anti-IL-20 neutralizing antibody administration ameliorated MCAO-induced brain infarction in rats." (PMID 33790691, 2021).
Cachexia (1 paper, 2022). Severe weight loss, wasting of muscle, loss of appetite, and general debility related to a chronic disease. "This was in line with the previous finding that attenuated weight loss and reduced lipolysis of adipose tissues occurred in tandem with fewer macrophage infiltration after treatment of anti-IL-20 monoclonal antibodies in Lewis lung carcinoma-induced cachexia model." (PMID 36376273, 2022).
candidiasis (1 paper, 2022). Infection with the organism Candida. "The results support the hypothesis that inhibition of protective immunity by IL-20 signaling in B6 mice is detrimental to recovery from candidiasis, especially in the presence of strains with elevated virulence." (PMID 36225230, 2022).
cellulitis (1 paper, 2015). Inflammation of the dermis and subcutaneous tissues caused by a bacterial infection. "One serious AE (SAE) was reported in the trial, during the MD dose-escalation phase (moderate cellulitis reported 19 days after the fourth and final dose of 0.05 mg/kg anti‒IL-20), but this SAE was judged as having no causal relationship to the study drug." (PMID 26252485, 2015).
Cerebral ischemia (1 paper, 2022). Restriction of arterial blood supply to the brain associated with insufficient oxygenation to support the metabolic requirements of the tissue. "After cerebral ischemia reperfusion, the levels of IL-20 in serum and ischemic penumbra were significantly elevated than sham groups, and glial cells were the main source of IL-20." (PMID 35173738, 2022). "After cerebral ischemia, hypoxia also induces the production of IL-20 in endothelial cells." (PMID 35173738, 2022).
cervical cancer (1 paper, 2023). A primary or metastatic malignant neoplasm involving the cervix. "In addition, LINE-1 hypomethylation promotes IL20 expression in cervical cancer, induces altered signaling pathways, and increases cell invasiveness, which is an important epigenetic alteration in several cancers, including gynecologic tumors." (PMID 37546391, 2023).
chronic hepatitis B infection (1 paper, 2021). "Moreover, it has been shown that some polymorphism in IL-19 and IL-20 genes could worsen the outcome of chronic hepatitis B infection and septic shock." (PMID 34944654, 2021).
delirium (1 paper, 2023). A disorder characterized by confusion; inattentiveness; disorientation; illusions; hallucinations; agitation; and in some instances autonomic nervous system overactivity. "Again, delirium was associated mostly with higher expression, but the inverse was true preoperatively for myoglobin (MB), IL-2, and IL-20, and postoperatively for chemokine ligand 15 (CCL15) and TNF-related apoptosis-inducing ligand (TRAIL)." (PMID 37156856, 2023).
dermopathy (1 paper, 2021). "Consistent with previously published studies, the abnormal expression of cytokines, such as IL-20 and IL24, was also found in the skin of patients with dermopathy." (PMID 33763026, 2021).
esophageal squamous cell carcinoma (1 paper, 2018). Esophageal squamous cell carcinoma (ESCC) is a type of esophageal carcinoma (EC) that can affect any part of the esophagus, but is usually located in the upper or middle third. "Increased expression of IL-19 and IL-20 in esophageal squamous cell carcinoma has been reported, but potential mechanisms how members of the IL-20 cytokine family support the development of squamous cell carcinoma and adenocarcinoma in the esophagus is not known yet." (PMID 29967613, 2018).
glaucoma (1 paper, 2016). Increased pressure in the eyeball due to obstruction of the outflow of aqueous humor. "Based on these findings, this IL-20RB mutation is highly likely to impact the IL-20 signaling pathway, which may contribute to the pathogenesis of glaucoma in this family." (PMID 26903709, 2016). "While the IL-20RB mutation most likely is not a causative factor in the majority of glaucoma cases, the identification of this mutation has revealed that defective IL-20 signaling may lead to glaucoma in this large POAG pedigree." (PMID 26903709, 2016). "Second, IL-20 stimulation of the mutant IL-20RB leads to abnormal STAT3 activation and MMP activity in glaucoma fibroblasts." (PMID 26903709, 2016). "IL-20, IL-24, IL-20RA, and IL-20 RB are expressed in the retina and optic nerve head in the DBA/2J mouse model of glaucoma (see later)." (PMID 26903709, 2016).